CTNNB1 (catenin beta 1)
Diseases named in the same sentence as CTNNB1 in open-access papers (continued):
Sharing a sentence is not in itself a finding about the gene and the disease.
parathyroid tumors (5 papers, 2007 to 2021). "Abnormal Wnt signaling has been associated with many types of tumors, and deregulation of CTNNB1 as well as mutations of LRP5 coreceptor has been found in some series of parathyroid tumors." (PMID 22567348, 2011). "We recently reported aberrant β-catenin (CTNNB1) accumulation in all analyzed parathyroid tumors from patients with pHPT and in hyperplastic parathyroid glands from patients with uremia secondary to HPT." (PMID 18044981, 2007). "Parathyroid tumors did not harbor constitutively activated β-catenin pathways: Activating mutations of the CTNNB1/β-catenin gene are rare and nuclear β-catenin immunostaining has not been demonstrated so far." (PMID 34199594, 2021). "Of all 57 analyzed parathyroid tumors with accumulated β-catenin, 52 expressed the internally truncated LRP5 receptor without CTNNB1-stabilizing mutations, four tumors had CTNNB1-stabilizing mutations but no truncated LRP5 receptor, and 1 tumor displayed neither aberration." (PMID 18044981, 2007).
pulmonary fibrosis (5 papers, 2017 to 2026). Chronic progressive interstitial lung disorder characterized by the replacement of the lung tissue by connective tissue, leading to progressive dyspnea, respiratory failure, or right heart failure. "Mo-IMs in Ctnnb1 knockout mice preferentially differentiated into Mo-AMs, exacerbating pulmonary fibrosis." (PMID 41535251, 2026). "For example, DACH1 (LncRNA) can inhibit the activation of lung fibroblasts and the excessive deposition of the ECM by binding to SRSF1 and suppressing the expression of SRSF1 and CTNNB1 proteins, which helps alleviate pulmonary fibrosis." (PMID 40427668, 2025). "For example, SNHG5 is also involved in the p38/MAPK signal pathway, Wnt/CTNNB1, and other pulmonary fibrosis-related signaling pathways." (PMID 34349786, 2021). "Moreover, 4 weeks after bleomycin treatment, there was a marked increase in lung fibrosis in Ctnnb1-knockout mice, as assessed by anti-PDGFRa, anti-PDGFRb, anti-collagen I, and anti-collagen IV immunofluorescence staining and Sirius red staining of lung sections." (PMID 41535251, 2026).
retinal detachment (5 papers, 2017 to 2022). An eye emergency condition which may lead to blindness if left untreated. "The retinal detachment had only been reported in two Asian patients, and we firstly reported the phenotype of polydactyly in the CTNNB1 mutation." (PMID 33425807, 2020).
spastic diplegia (5 papers, 2020 to 2024). A type of cerebral palsy characterized by spasticity and hypertonia of the lower extremities bilaterally, particularly the legs, hips, and pelvis; this is the most common (70%) form of cerebral palsy. "Our findings seem to confirm the existence of sex bias in the neurodevelopmental disorder with spastic diplegia and visual defects caused by variants in CTNNB1, as all our patients are females." (PMID 34946966, 2021). "Interestingly, CTNNB1 (MIM: 116806) has been linked to autosomal dominant neurodevelopmental disorder with spastic diplegia and visual defects (MIM: 615075), making TLE3 an even more plausible candidate for impacting the patient phenotype." (PMID 32344861, 2020).
Strabismus (5 papers, 2017 to 2022). A misalignment of the eyes so that the visual axes deviate from bifoveal fixation. "Three patients were found with strabismus, which supports the observation that ocular abnormalities are frequent findings in patients with CTNNB1-associated neurodevelopmental disorder." (PMID 34946966, 2021).
cardiac hypertrophy (4 papers, 2014 to 2023). "A recent study has shown that PM2.5 exposure can induce cardiac hypertrophy via circRNA_0001859, which suppressed miR-29b-3p, resulting in an enhanced Ctnnb1 level and activated the downstream pathway molecules like LEF1/IGF-2R." (PMID 37626874, 2023).
cardiomyopathy (4 papers, 2016 to 2025). A disease of the heart muscle or myocardium proper. "Ctnnb1 overexpression in arterial ECs of the heart has been reported previously to cause cardiomyopathy." (PMID 34658910, 2021). "In addition, stem-like genes such as CTNNB1, MYC, and HIF1A may also attenuate heart failure after cardiomyopathy." (PMID 40717095, 2025).
colorectal adenocarcinoma (4 papers, 2022 to 2023). The most common type of colorectal carcinoma. "We searched the TCGA database for the presence of altered APC, β-Catenin (CTNNB1) and GSK3β in 526 colorectal adenocarcinoma patient samples (TCGA, PanCancer Atlas)." (PMID 35625868, 2022). "To obtain an insight into the functional role of CTNNB1 (β-Catenin) gene expression in CRC growth, we performed an in-silico transcriptomic analysis in a dataset of colorectal adenocarcinoma patients." (PMID 35625868, 2022). "Using TCGA colorectal adenocarcinoma Firehose legacy dataset from cBioPortal platform, we found that the TFRC protein expression was positively correlated with the CTNNB1 protein expression, whereas the CTNNB1 protein expression was negatively correlated with APC mRNA expression." (PMID 36703617, 2023).
COVID-19 (4 papers, 2022 to 2025). A disease caused by infection with severe acute respiratory syndrome coronavirus 2. "There was greater tissue expression of CTNNB-1 (β-catenin) in COVID-19 samples compared to the CONTROL and H1N1 groups." (PMID 36992415, 2023). "The increased expression of TNF-α, NF-kB, VEGF, VEGFR-1, GJA-1 (Connexin-43), and CTNNB-1 (β-catenin) in the COVID-19 group suggests a strong activation of angiogenic pathways in response to hypoxia and hyperinflammation associated with SARS-CoV-2 infection." (PMID 36992415, 2023). "Uncontrolled interactions of CTNNB1 with PSEN149 and GLI250 are linked to skin tumorigenesis, which may be suggestive for their possible involvement in COVID-19." (PMID 36229517, 2022). "Our network pharmacology analysis revealed that CTNNB1 was among the top 10 common targets shared by AST IV, IAV, and COVID-19." (PMID 40307893, 2025). "Four proteins (CTNNB1, HIF-1α, VEGF and ANGPT) related to the 22 mRNAs described for COVID-19 were analyzed." (PMID 36992415, 2023). "Some genes that may be related to severe COVID-19 pathophysiology and are good candidates for experimental investigation include PRKG1, ACE, CFB, CRP, CTNNB1, EGFR, and VEGFA." (PMID 35794133, 2022). "The ‘prevalent’ ‘candidate genes’ (ADAM10, ADAM17, AKT1, CTNNB1, ESR1, FGFR1, PIK3CA) might have the most prominent pathophysiological relevance in COVID-19." (PMID 36229517, 2022).
depression (4 papers, 2019 to 2025). "Based on the network topology combined with the PPI analysis, we obtained that TCEF can regulate depression through five core targets, namely, ALB, AKT1, TNF, ESR1, and CTNNB1." (PMID 36506595, 2022). "UHPLC-Q-EOMS was employed to identify 59 major components of TCEF, and network pharmacology analysis was used to screen 48 active components of TCEF for treating depression, corresponding to 139 relevant targets, including ALB, AKT1, TNF, ESR1, and CTNNB1." (PMID 36506595, 2022). "In total, these findings suggest that SLC39A8 and CTNNB1 might contribute to psychogenic ED through changes invoked in the amygdala, and provide a possible mechanism for the moderate genetic correlations we found for EHR-ED with depression and PTSD." (PMID 41285899, 2025).
fibrosis (4 papers, 2019 to 2024). the formation of excess fibrous connective tissue in an organ or tissue in a reparative or reactive process. "In these paths, the IPF node is directly connected to either EMT pathway nodes (SNAI2, TWIST1 and ZEB1) or dinoprostone (a pulmonary fibrosis regulator that expresses β-catenin), which is linked to CTNNB1." (PMID 38349059, 2024). "Some proteins of these genes have already been associated with pathophysiological processes in the kidney: in tubulointerstitial fibrosis (c-MYC, PTEN, STAT3, HIF-1α, PT53); podocyte injury (EGFR, PT53, CTNNB1, CREB1); epithelial-mesenchymal transition (PTEN); and glomerulosclerosis (DICER1, IL1β)." (PMID 37035314, 2023).
Gardner syndrome (4 papers, 2020 to 2025). Gardner syndrome is a severe form of familial adenomatous polyposis characterized by multiple adenomas in the colon and rectum associated with prominent extracolonic features including osteomas and multiple skin and soft tissue tumors. "While most sporadic DTF harbor somatic mutations in CTNNB1, germline mutations in adenomatous polyposis coli (APC) are known to occur in hereditary DTF types (FAP, Gardner-Syndrome)." (PMID 32099073, 2020). "In most cases this reflects somatic, stabilizing mutations of CTNNB1 (β-catenin; 85–90%), which promote nuclear β-catenin accumulation and transcriptional activation; 10–15% of cases are instead related to germline APC mutations (FAP/Gardner syndrome)." (PMID 41227209, 2025).
gynecologic cancer (4 papers, 2019 to 2025). "Furthermore, somatic mutations of CTNNB1 were predominantly observed in ECs compared with other gynecologic cancer types (P = 3.153 × 10−03, Fisher’s exact test), indicating that targeting of Wnt/ß-catenin pathway could potentially provide clinical benefits for EC patients." (PMID 31771620, 2019). "CTNNA1, CTNNB1 and CDH1 expressions were found to be suppressed in EC as well as other gynecological cancers, and further decreased with advanced invasion, contributing to cell-to-cell junctional dysfunction." (PMID 37313172, 2023).
head and neck squamous cell carcinoma (4 papers, 2018 to 2023). A squamous cell carcinoma that arises from any of the following anatomic sites: lip and oral cavity, nasal cavity, paranasal sinuses, pharynx, larynx, and salivary glands. "In head and neck cancer, which presents primarily as head and neck squamous cell carcinoma (HNSCC), mutations in CTNNB1 are relatively infrequent." (PMID 30029671, 2018).
Hepatitis (4 papers, 2008 to 2025). Inflammation of the liver. "In line with this, 84% of CTNNB1 mutations in our study were detected in hepatitis‐infected HCC cases." (PMID 40344393, 2025). "In addition, CTNNB1 mutations (D32N/Y, S33C/Y, S34V, S37P, T41A, and S45P) were detected in 93.75% of hepatitis‐related HCC cases, showing a strong correlation between these mutations and hepatitis virus‐associated HCC." (PMID 40344393, 2025). "Furthermore, CTNNB1 mutations were frequently observed in HCC patients with hepatitis, indicating their potential relevance." (PMID 40344393, 2025). "In this study, we investigated the prevalence of TERTp and CTNNB1 exon 3 mutations, as well as TERT gene expression, in HCC, cirrhotic, and hepatitis tissues from Brazilian patients." (PMID 40650279, 2025). "As expected, these mutations were nearly absent in cirrhotic and hepatitis tissues, corroborating the idea that CTNNB1 mutations typically arise later in the carcinogenic cascade and are rare in precursor lesions." (PMID 40650279, 2025).
intestinal cancer (4 papers, 2016 to 2025). "This may indicate that the tumor promoting function of Pygo2 in the Ctnnb1 GOF model may be partly regulated by the induction of Lgr5-positive stem-like cells that are known to be the origin of intestinal cancer." (PMID 27811361, 2016).
metastatic cancer (4 papers, 2006 to 2022). A carcinoma which has spread from the original site of growth to another anatomic site. "Examples of these unique genes include Serpine2, which is overexpressed in metastatic cancer; Ctnnb1, Fliih, Pdlim4/Ril, all of which affect migratory behavior of cells; and Gas6, which is a ligand for the Axl oncogene." (PMID 17147824, 2006). "Since the pathways such as PI3K (AKT) and MAPK are significantly upregulated in metastatic cancers, we performed the Western blot to see the effect at a protein level after intracellular delivery of CTNNA1 and CTNNB1 siRNAs using CA nanoparticles in 4T1 cells." (PMID 31269666, 2019).
myopia (4 papers, 2018 to 2024). "Several targets of these miRNAs, e.g. GNAS, TRAM1, CTNNB1, EIF4B, TENM3 and RUNX were previously associated with myopia/HM/refractive error in Europeans in genome-wide association studies." (PMID 36685896, 2022). "FI network analysis revealed important network modules and regulator linker genes (EP300, CTNNB1) potentially related to high myopia development." (PMID 30245926, 2018). "Thus, CTNNB1’s role in myopia may be attributed to its influence on the Wnt signaling pathway." (PMID 39625993, 2024).
neuroendocrine tumors (4 papers, 2020 to 2025).
ocular melanoma (4 papers, 2022 to 2023). A melanoma that arises from the structures of the eye or ocular adnexa. "YTHDF3 promotes the translation of the catenin beta 1 (CTNNB1) and contributes to ocular melanoma propagation." (PMID 36835633, 2023).
pancreatic adenocarcinoma (4 papers, 2011 to 2025). "The pan-cancer survey of distinct tumor types from patients revealed that TRIM69 was recurrently upregulated in nearly all tumors including pancreatic adenocarcinoma (PAAD), which also contained much higher levels of Ctnnb1 and Id2 than the normal controls." (PMID 36741265, 2023). "The expression levels of CTNNB1, RELA, TWIST1, and YAP1 in pancreatic adenocarcinoma (PAAD) tissues were higher than those in corresponding normal tissues." (PMID 40124511, 2025).
pancreatic ductal adenocarcinoma (4 papers, 2018 to 2022). An infiltrating adenocarcinoma that arises from the epithelial cells of the pancreas. "CTNNB1 encoding of B-catenin and Wnt/B-catenin aberrant signaling could lead to the development of cancers such as controversial pancreatic ductal adenocarcinoma." (PMID 35154607, 2021). "One pilot study reported the role of REG3A in modulating pancreatic ductal adenocarcinoma which interacts with WNT/CTNNB1 and TGF-beta pathways." (PMID 31940813, 2020). "Transcriptome profile showed elevated TCF7, CTNNB1, and JUN expression in pancreatic ductal adenocarcinoma." (PMID 36457029, 2022).
Papillary Craniopharyngioma (4 papers, 2017 to 2024). A craniopharyngioma composed of sheets of squamous epithelium which separate to form pseudopapillae. "Interestingly, papillary craniopharyngioma is also caused by BRAF Val600Glu instead of a CTNNB1 mutation." (PMID 28658279, 2017).
primary aldosteronism (4 papers, 2017 to 2025). An endocrine disorder characterized by excessive production of aldosterone by the adrenal glands. "While the Wnt pathway seems crucial for adrenal development of the zona glomerulosa, it remains thus uncertain if mutations of CTNNB1 specifically plays a role in HCG-responsive primary aldosteronism." (PMID 36926028, 2023). "However, a case report of a Japanese female patient with the same double mutations (GNA11/Q and CTNNB1) presented with primary aldosteronism and hypokalaemia despite having a normal menstrual cycle and in the absence of pregnancy-induced hypertension." (PMID 40725432, 2025). "The involvement of somatic CTNNB1 mutations in the induction of LHCGR and GnRHR ectopic expression and pregnancy-LH/HCG stimulated primary aldosteronism has been questioned." (PMID 36926028, 2023).
rectal cancer (4 papers, 2017 to 2023). A primary or metastatic malignant neoplasm that affects the rectum.
rhabdomyosarcoma (4 papers, 2017 to 2025). A rare aggressive malignant mesenchymal neoplasm arising from skeletal muscle. "Also, further studies on the discovered mutations in genes such as CTNNB1, BCOR, FBXW7, and others may provide targets for novel treatments in patients with rhabdomyosarcoma." (PMID 35530877, 2022).
soft tissue tumor (4 papers, 2019 to 2025). "Immunohistochemical staining for β-catenin and CTNNB1 mutation analysis are crucial for distinguishing DF from other soft tissue tumours." (PMID 40558263, 2025). "Desmoid tumours (DES), a locally aggressive soft tissue neoplasm that lacks metastatic potential and harbours CTNNB1 mutations have also been included in the cohort." (PMID 37386008, 2023). "DTs are a rare and locally invasive soft tissue tumor characterized by catenin beta-1 (CTNNB1) or adenomatous polyposis coli (APC) mutations." (PMID 31665941, 2019). "Other soft tissue tumors and scar tissues may harbor CTNNB1 mutations or exhibit nuclear β-catenin expression." (PMID 39881334, 2025).
Stroke (4 papers, 2019 to 2023). Sudden impairment of blood flow to a part of the brain due to occlusion or rupture of an artery to the brain. "Our results suggest an association between CTNNB1 and p75NTR possibly demonstrating a substantial role for p75NTR in the stroke response." (PMID 32917932, 2020). "LRRK2, CALM1, CXCR4, TLR4, CTNNB1, and CXCR2 may be implicated in AF and the hub-genes of CD19, FGF9, SOX9, GNGT1, and NOG may be associated with stroke." (PMID 30760287, 2019).
synovial sarcoma (4 papers, 2022 to 2026). "The most common molecular alterations (excluding canonical SS18::SSX fusions in synovial sarcoma) involved ATM (18%), ARID1A (9%), CTNNB1 (9%), PALB2 (9%), and NF1 (9%), while 46% of profiled cases showed no detectable alterations." (PMID 41504936, 2026).
adenomyosis (3 papers, 2022 to 2023). The growth of endometrial tissue inside the muscular wall of the uterine corpus. "Neonatal dosing of the SERM compounds, such as tamoxifen and toremifene, also caused adenomyosis in adult mice and the development of Ctnnb1-induced adenomyosis in mice required the presence of estrogen." (PMID 35563206, 2022).
anaplastic carcinoma (3 papers, 2014 to 2024). "The CTNNB1 gene has point mutations in exon 3 found in more than half of anaplastic carcinomas (up to 60%)." (PMID 33669363, 2021). "CTNNB1 represents another frequently mutated gene in anaplastic carcinoma, which encodes a molecule involved in cell adhesion and Wnt signaling called β-catenin." (PMID 33669363, 2021).